IL33 (interleukin 33)
Diseases named in the same sentence as IL33 in open-access papers (continued):
Sharing a sentence is not in itself a finding about the gene and the disease.
cancer (continued). "The tumor cells secrete interleukin-33 cytokine, which causes myeloid cell differentiation into macrophage and consequently stimulates TGF-β signals to reach cancer stem cells, resulting in the progression of malignant tumors and drug resistance." (PMID 40548119, 2025). "IL-33 overexpression has been observed in several cancers, including breast cancer, colorectal cancer, lung cancer, and head and neck cancer." (PMID 40647388, 2025). "IL-33 and IL-18 have been identified as the signalling mediators involved in cancer development and progression." (PMID 40247153, 2025). "IL-33 is expressed in endothelial cells, epithelial cells, and fibroblast-like cells, making it present in multiple organs, and its functions in cancer and allergic inflammation are well-recognized." (PMID 41048933, 2025). "Recently, IL-33 has been reported to be actively involved in promoting the therapeutic resistance of cancer cells by several groups." (PMID 40216748, 2025). "This suggests that the upregulation of COL11A1 and the downregulation of CAV1, CXCL12, and SPTBN1 in the cancer microenvironment led to the downregulation of IL-6 and IL-33." (PMID 40898538, 2025). "Another report demonstrated that cancer-associated fibroblasts in head and neck SCC displayed abundant IL-33 expression, with most of the highly invasive cases showing IL-33 overexpression in both the cancer-associated fibroblasts and cancer cells." (PMID 41374934, 2025). "IL-33 is an alarmin cytokine induced in response to cellular injury, which has pro- and anti-cancer effects in various contexts." (PMID 40579434, 2025). "Herein, we provide un updated literature review on the role of eosinophils in cancer development and immune response, and the functions of some cytokines, including IL-31 and IL-33, in eosinophil activation." (PMID 40305195, 2025). "IL33 was found to have widespread positive correlations in several cancer types, whereas IRF9 and TRAF5 demonstrated more heterogeneous correlation profiles." (PMID 40893939, 2025). "Interleukin 33 (IL-33) has emerged as a crucial factor involved in the pathogenesis of cancer-prone chronic inflammation." (PMID 40647388, 2025). "Tregs suppress immune response in different types of cancer, and MCs interact with Inducible T-cell co-stimulator (ICOS)+ Tregs through IL-33 and IL-2 and promote cancer progression." (PMID 41425713, 2025). "IL-33 induced by TLR3/4-TBK1-IRF3 signaling pathways drives cancer-prone chronic inflammation in the skin and pancreas." (PMID 40579434, 2025). "First, cancer stem cells can establish an IL-33-TGF-β niche signaling loop to drive immunosuppressive TME and drug resistance." (PMID 40216748, 2025). "For instance, elevated IL‐33 serum levels are positively correlated with poor prognosis in various cancer types." (PMID 40751595, 2025). "Overexpression of IL-33 has been associated with chemotherapy resistance, migration, and metastasis in various cancers, and IL-33 can promote lung tumorigenesis and metastasis via type 2 innate lymphoid cells (ILC2s)." (PMID 41272907, 2025). "Recent studies have drawn attention to the biological role of the IL-33/ST2 axis in its effects on malignant tumors." (PMID 40520454, 2025). "Because of its important role in the inflammatory response, IL‐33 is expected to be a novel therapeutic target and predictor for cancer." (PMID 40860436, 2025). "The levels of IL8 and IL17A were higher in the cancer group, while the level of IL33 was higher in the healthy group." (PMID 38398137, 2024). "Here, the authors show that TLR3/4-TBK1-IRF3 pathway activation induces IL-33, and the cholesterol-lowering drug, statin, blocks this pathway to suppress chronic inflammation and its cancer sequela." (PMID 38816352, 2024). "In this study, we measured the concentration of IL33 in the serum of cancer patients and healthy controls." (PMID 38398137, 2024).
cancer (continued). "Understanding the delicate cooperation between IL-33 and DC-based antitumor effects provides valuable insights for tailoring therapeutic strategies harnessing IL-33 in the complex landscape of cancer immunotherapy." (PMID 38825642, 2024). "Due to its immunomodulatory properties, IL-33 has the potential to synergize with various cancer therapies, including immune checkpoint blockade and chemotherapy." (PMID 40236667, 2024). "We found a significant difference between the two groups, with healthy controls having a higher mean concentration of IL33 (121.40 pg/mL) than cancer patients (42.47 pg/mL)." (PMID 38398137, 2024). "The negative correlation with MSI score, mRNAsi, and EREG‐mRNAsi, along with increased sensitivity to doxorubicin in patients with high IL33 expression, adds depth to our understanding of its role in cancer therapy." (PMID 38923705, 2024). "Regarding this immunomodulatory activity, IL-33 demonstrates synergistic interactions with various cancer therapies, including immune checkpoint blockade and chemotherapy." (PMID 38881897, 2024). "Both animal and human studies are necessary to fully understand how the IL-33/ST2 axis contributes to these cancers." (PMID 40236667, 2024). "In the landscape of cell-based cancer immunotherapies, an uncharted territory involves Type 2 innate lymphoid cells (ILC2s) and interleukin-33 (IL-33) which promotes ILC2 functionality, recognized for their inherent ability to enhance immune responses." (PMID 38524132, 2024). "Overall, the scientific evidence provided in this study lays a foundation for future investigations aiming to leverage the IL-33/ILC2 axis for therapeutic interventions in cancer." (PMID 38524132, 2024). "In some tumors, IL-33 is highly expressed in normal epithelial cells but downregulated in cancer cells in advanced conditions." (PMID 40236667, 2024). "Herein, we identify TLR3/4-TBK1-IRF3 signaling as the critical regulator of IL-33 expression and discover statin to suppress IL-33 expression by regulating TBK1 signaling in cancer-prone chronic inflammation." (PMID 38816352, 2024). "We previously demonstrated that IL-33 promotes contact-dependent cytotoxic function of eosinophils against various cancer cell types." (PMID 39061080, 2024). "On the other hand, the concentration of interleukin 33 (IL33) was higher in the healthy group than in the cancer group, suggesting a protective role of this cytokine against cancer development." (PMID 38398137, 2024). "Interleukin‐33 (IL‐33) exerts antitumor effects through various mechanisms, including enhancing antitumor immunity and promoting the apoptosis of cancer cells." (PMID 38737470, 2024). "The elucidation of IL33's biological functions in the HCC microenvironment holds significant implications for its role in cancer pathogenesis." (PMID 38923705, 2024). "The top upregulated gene in the LoGI group was IL-33, a cytokine currently being studied as a potential therapy for immune homeostasis and for its role in cancer immune-surveillance." (PMID 38082056, 2024). "Our in vitro data indicated that cisplatin promoted IL-33 release in cancer cells, while α-IL-33 and α-ST2L reversed the Cis-CM-induced M2 macrophages." (PMID 38778059, 2024). "In recent years, IL-33 has been described as a potent initiator of type 2 immune responses, acute local inflammation, and tissue repair, promoting cancer development and remodeling the TIME by increasing the number of immune-suppressive cells." (PMID 38238529, 2024). "The findings indicated differential expression of IL33 across various cancer types, suggesting its potential role in cancer development." (PMID 38923705, 2024). "IL-33/ST2 signaling is involved in numerous cancers, exhibiting both protumor and antitumor functions." (PMID 40236667, 2024). "This research began to unravel the intricate relationship between IL-33, ILC2s, and their collective impact on the body’s ability to combat cancer." (PMID 38524132, 2024).
cancer (continued). "IL-33, an alarmin cytokine of the IL-1 family, is produced by various cells, including cancer cells." (PMID 39206193, 2024). "Macrophage intervention combined with IL-33 can induce strong and long-lasting protection against cancer and eradicate various tumors under such conditions." (PMID 38238529, 2024). "IL33 exhibited differential expression across cancers, particularly in endothelial cells within the HCC microenvironment." (PMID 38923705, 2024). "Genomic features, drug sensitivity analyses and pan‐cancer assessments provided valuable insights into the broader implications of IL33." (PMID 38923705, 2024). "Emerging evidences suggested that IL‐33 exerts antitumor effects through various mechanisms, including enhancing antitumor immunity, inhibiting proliferation, and promoting apoptosis of cancer cells." (PMID 38737470, 2024). "IL-33 is a pro-inflammatory cytokine of the IL-1 superfamily and plays a vital role in inflammation, and cancer, and central nervous system diseases." (PMID 39350187, 2024). "Several studies have shown that IL‐33 also has significant antitumor efficacy by suppressing proliferation and inducing apoptosis of cancer cells." (PMID 38737470, 2024). "To identify a small molecule IL-33 inhibitor that can safely alleviate chronic inflammation and its cancer sequela, we screened an FDA-approved drug library in a luciferase-based Il33 expression assay." (PMID 38816352, 2024). "These processes are well‐established hallmarks of cancer development, signifying IL33's involvement in promoting key aspects of malignancy." (PMID 38923705, 2024). "We investigated the IL‐33 expression levels of MM cell lines in Cancer cell Line Encyclopedia (CCLE) database." (PMID 38737470, 2024). "In this study, the IL-33 expression, in carcinoma cells, was positive in 49.43% (20.69% had high expression and 28.74% had low expression) while the VEGF expression was positive in 29.89% (6.90% had high expression and 22.99% had low expression)." (PMID 38313904, 2024). "Specifically, the high expression of IL-33 would increase the histological grade differentiation of cancer, increase the possibility of distant metastasis, and make tumors larger in size and later stage." (PMID 37507682, 2023). "As such, PPARγ drives pro-tumoral functions of group 2 innate lymphoid cells (ILC2) which protect against infection by helminths via the release of IL33, an alarmin overexpressed in cancers." (PMID 37686465, 2023). "The type 2 immunity-related cytokines IL-25 and IL-33 with recently discovered roles in cancer are also explored in light of their potential as novel immunotherapeutic targets." (PMID 37455828, 2023). "Data from this analysis indicated that cancer patients with high IL-33 expression had a poorer prognosis." (PMID 37507682, 2023). "Overexpression of IL-33 in cancer can increase the antitumor immune response by activating CD8+ T and natural killer cells." (PMID 37176567, 2023). "IL-33 is a novel contributing factor in tumorigenesis and plays a critical role in regulating angiogenesis and cancer progression in a variety of human cancers." (PMID 37296602, 2023). "The literature shows contrasting results, suggesting that the role of IL-33 in cancer development and growth remains to be clarified." (PMID 37296602, 2023). "The inducing effects of intratumoral fungi on the IL-33/ILC2 axis potentially have variable consequences according to the cancer type, location and the state of the TME." (PMID 37868956, 2023). "The complex and multifaceted roles of IL-33 in cancer pharmacotherapy necessitate a thorough understanding and careful consideration of its direct and indirect effects." (PMID 37762328, 2023). "Despite the encouraging results observed in preclinical models, much remains to be elucidated regarding the diverse roles of IL-33/ST2 in different cancer stages, types, and responses to treatment." (PMID 37762328, 2023).
cancer (continued). "To reduce the heterogeneity of the included studies, we compared the serum IL-33 levels of different cancer type subgroups and control groups." (PMID 37507682, 2023). "Our findings demonstrate that blocking the TBK1-IRF3 signaling pathway suppresses IL-33 expression and cancer-prone chronic inflammation." (PMID 36711701, 2023). "IL-25 and IL-33 are well-established type 2 immune-related cytokines with recently discovered roles in cancer immunity." (PMID 37455828, 2023). "A total of 9 studies were included in the analysis to study the relationship between IL-33 expression and the prognosis of cancer patients." (PMID 37507682, 2023). "Further investigations on the role of IL-33 are required, as it varies heavily based on cancer type and the TME composition." (PMID 37514187, 2023). "Another possible effect of IL-33/ST2 signaling is the increase of CRC malignancy mediated by the induction of cancer stem cell-like CRC cells." (PMID 37296602, 2023). "In regard to TME composition, we found high amounts of SCF and IL-33, similar to previous finding obtained in human malignant tumors and a genetic mouse model of CRC." (PMID 37730723, 2023). "Meanwhile, we collected comprehensive literature on IL-33 and the clinical characteristics of cancer patients retrieved from the PubMed, Web of Science and CNKI databases as of December 2022." (PMID 37507682, 2023). "IL-33 primarily activates natural killer cell, which plays an important role in regulating angiogenesis and cancer progression in GC." (PMID 38154092, 2023). "Those latter findings are consistent with yet other findings showing that Il33-null mice are more susceptible to DSS-induced injury and colitis-associated cancer." (PMID 37014710, 2023). "Intratumoral fungi Alternaria alternata and M. globosa actuated the dectin-1 signaling pathway in cancer cells that promoted KrasG12D-mediated IL-33 release." (PMID 37868956, 2023). "Herein, we examined the effects of CVC on the mRNA and protein levels of CCR2, CCL2, VEGF, NF-κB, c-Myc, IL33, and vimentin, which are involved in the progression of cancer." (PMID 37325423, 2023). "A recent study suggested that cancer-cell-derived IL-33 is necessary to synergize with Cytotoxic T-Lymphocyte-Associated protein 4 (CTLA-4) or Programmed Cell Death 1 (PD-1) monoclonal antibodies (mAbs) to enhance antitumor efficacy." (PMID 37762328, 2023). "Regarding the role of IL-33 in cancer pharmacotherapy, the crux is understanding its direct and indirect effects." (PMID 37762328, 2023). "IL-33 is highly expressed in the serum of cancer patients and is also found in cancer cells and cancer-associated fibroblasts (CAFs)." (PMID 37176567, 2023). "IL33 is an alarmin important for immunity, inflammation, epithelial barrier function and cancer, and it was the most upregulated signaling factor following IL11 exposure." (PMID 36012165, 2022). "Although fungal pancreatic oncogenesis occurs via complement cascade activation and IL-33 secretion, little is known about fungal functional repertoires in other cancers." (PMID 36179670, 2022). "Secretion of IL-33 by CAFs is stimulated by TNF from cancer cells in a NF-κB-IRF-1-dependent manner." (PMID 35163805, 2022). "Earlier reports have demonstrated that IL-33 activates the MAPK pathways in various cancer cell lines, and showed an IL-33/ST2-dependent NF-κB activation." (PMID 35409061, 2022). "Co-culturing of human NSCLC cells with IL-33 antagonists reduces M2 polarization and Treg cell accumulation, inhibiting the growth of cancer cells." (PMID 36291105, 2022). "This activation enhanced the proliferation and migration of cancer cells, and facilitated the expression of IL-33 cytokine by DLL3 and the degradation of LG3BP and HSPA8." (PMID 35382168, 2022). "It has been suggested that lung group 2 innate lymphoid cells (ILC2), which produce IL-5 or IL-13 in response to IL-25 and IL-33, suppress the lung metastasis of cancer cells." (PMID 34170380, 2022).
cancer (continued). "P25 TRAMP CRIPSCs also had upregulated genes related to cancer development and drug resistance, such as Aldh3a1, Ly6d, Il33, Dsg3, and Col17a1." (PMID 35841025, 2022). "In turn, IL-33 activates the ERK1/2-SP1-ZEB2 pathway in cancer cells, and this promotes their migration and invasion." (PMID 35163805, 2022). "IL33 is upregulated in diverse types of cancers, particularly in GC and CRC, and the IL33-mast-TAM axis has been reported as a poor prognostic factor in GC patients." (PMID 36211375, 2022). "They reported that high IL-33 level in cancer cells and in CAFs is a good prognostic marker of survival." (PMID 35804329, 2022). "In a mouse CRC cell line implant model, transgenic overexpression of IL-33 in MC38 cells (MC38-IL-33) resulted in 3-fold higher microvessel density and increased cancer metastasis to the liver compared to vector control." (PMID 36263033, 2022). "IL33 is also released from many other cells, such as endothelial cells, epithelial cells, fibroblasts, and cancer cells, upon cellular stress." (PMID 36211375, 2022). "These cells also serve as a primary source of TNF-α, which suppresses expression of the alarmin IL-33 in carcinoma cells." (PMID 36256464, 2022). "Mechanistically, TNF-α, predominantly secreted by TAMs, decreases the expression of the alarmin IL-33 in carcinoma cells." (PMID 36256464, 2022). "The IL‐33‐TAM‐MMP‐9 signaling is a novel immunosuppressive pathway by shedding antigen in cancer cells and antigen recognizing surface molecules in T cells." (PMID 34486239, 2021). "Although the significance of IL‐33 has been reported previously for the development of several cancers, the relationship between IL‐33 and effective antitumor medications remained unclear." (PMID 34664425, 2021). "Targeting the IL‐33‐TAM‐MMP‐9 axis provides a novel therapeutic paradigm for treating various cancers by enhancing the effectiveness of immunotherapeutics." (PMID 34486239, 2021). "Interleukin-33 (IL-33) is a new cytokine belonging to the IL-1 family, it plays an important role in cancers and human immunopathology." (PMID 34778224, 2021). "By contrast, the IL‐33‐educated MMCs and HMCs completely protected cancer cells from the STIL‐mediated killing." (PMID 34486239, 2021). "These contrasting results suggest that the role of IL-33 in cancer development and growth must still be clarified." (PMID 34071419, 2021). "We showed that IL-33 induced LPIN1 expression by regulating JNK/c-Jun signaling by activating the Cancer Osaka thyroid (COT)." (PMID 33946554, 2021). "Expression of IL-33 in TILs was less common in cancers of the tongue and the floor of the oral cavity (p = 0.055, chi-square), but no other association between IL-33 and clinicopathological variables was found." (PMID 34572318, 2021). "This study has established a critical role of Eomes in limiting sustained efficacy of IL33-based and PD-1 blockade cancer immunotherapy." (PMID 33553191, 2021). "Cancers of the tongue and the floor of the oral activity expressed IL-33 less commonly (p = 0.001, chi-square)." (PMID 34572318, 2021). "We found that IL-33 has an antiproliferative and proapoptotic effect on cancer cell lines, and it can stimulate proliferation and reduce apoptosis in normal epithelial cell lines." (PMID 34071419, 2021). "We summarize and discuss the most recent studies on the contradictory effects of IL-33 on cancer progression and treatment, with a goal to better understanding the various ways for IL-33 as a therapeutic target." (PMID 34209038, 2021). "The cytokine IL-33 is of particular interest in the context of cancer stemness, as a number of studies have been recently published." (PMID 34583655, 2021). "IL‐33 operates the interactions between vascular/fibrotic cells and inflammatory macrophages to coordinately debilitate the cancer killing effect of cytolytic T cells by enhancing the proteolytic activity of MMPs." (PMID 34486239, 2021).